TUBB3 (tubulin beta 3 class III)
Diseases named in the same sentence as TUBB3 in open-access papers (continued):
Sharing a sentence is not in itself a finding about the gene and the disease.
heart failure (1 paper, 2016). Inability of the heart to pump blood at an adequate rate to meet tissue metabolic requirements. "Supporting the notion that the tubulin network is distorted in heart failure cells, mRNA expression analysis by qPCR confirmed an overall increase in the expression of α1A-tubulin (TUBA1A), β2B-tubulin (TUBB2B), β3-tubulin (TUBB3), γ-1tubulin (TUBG1), and microtubule-associated proteins (MAP4)." (PMID 26725114, 2016).
Hydrocephalus (1 paper, 2018). Hydrocephalus is an active distension of the ventricular system of the brain resulting from inadequate passage of CSF from its point of production within the cerebral ventricles to its point of absorption into the systemic circulation. "The patient, who, on a molecular level, was diagnosed with a de novo mutation p.(Thr106Met) in TUBB3, underwent ventriculo-peritoneal shunting because of a hydrocephalus at the age of 8 months." (PMID 30091983, 2018).
injury (1 paper, 2025). Damage inflicted on the body as the direct or indirect result of an external force, with or without disruption of structural continuity. "A study found that XFZYD could reverse the reduction of BDNF and TrkB in the hippocampus caused by traumatic brain injury and increase the number of synaptic connections, as well as the expression of synaptic-related protein PSD95, axon-related protein GAP43, and neuron-specific protein TUBB3." (PMID 40430532, 2025).
large cell carcinoma (1 paper, 2014). A malignant epithelial neoplasm composed of large, atypical cells. "Other studies in NSCLC have revealed that differences in histology (adenocarcinoma and large cell carcinoma), younger age and more advanced stage at diagnosis are correlated with higher TUBB3 expression." (PMID 24396456, 2014). "Furthermore, an analysis of 202 patients with advanced NSCLC revealed that high TUBB3 expression was found more often in patients with adenocarcinoma histology, large cell carcinoma histology, diagnosis at a younger age (<59 years) and higher stage disease at diagnosis (stage IV vs. III)." (PMID 24396456, 2014).
leiomyosarcoma (1 paper, 2018). An uncommon, aggressive malignant smooth muscle neoplasm, usually occurring in post-menopausal women. "We developed an eribulin-resistant leiomyosarcoma cell line to investigate the mechanism underlying resistance and found that TUBB3 overexpression induced chemoresistance to eribulin and knockdown of TUBB3 expression by siRNA led to chemosensitization to eribulin in the resistant cell line." (PMID 30034996, 2018). "In this study, we clearly reveal the critical role of TUBB3 in the acquisition of eribulin resistance in a leiomyosarcoma cell line." (PMID 30034996, 2018). "Because the level of TUBB3 expression was variable in leiomyosarcoma patients, TUBB3 has the potential to be a biomarker for selection of drug treatment." (PMID 30034996, 2018). "This is the first report to reveal the critical role of TUBB3 in the acquisition of eribulin resistance in a leiomyosarcoma." (PMID 30034996, 2018). "Our study is the first report to show expression levels in a large group of leiomyosarcoma patients and to elucidate the relationship with TUBB3 expression level and prognosis of the patients with leiomyosarcoma." (PMID 30034996, 2018). "Because high tumor growth is one of the major causes to make tumor aggressiveness, we considered that the patients with leiomyosarcoma which expressed high TUBB3 resulted in poorer prognosis than did the patients with low TUBB3." (PMID 30034996, 2018). "We found that the reduction of TUBB3 expression in the parental and resistant leiomyosarcoma cells resulted in a trend toward a decreasing cell proliferation rate, but the difference was not statistically significant (data not shown)." (PMID 30034996, 2018). "In addition, we analyzed tissue biopsy samples from two leiomyosarcoma patients treated with eribulin; one showed high levels of TUBB3 expression and the other showed low levels." (PMID 30034996, 2018). "In line with this, we showed that high TUBB3 expression induced resistance to eribulin in a leiomyosarcoma cell line and we hypothesize that the resistance to eribulin stems from TUBB3 overexpression." (PMID 30034996, 2018). "We also found that the level of TUBB3 expression was variable in leiomyosarcoma patients." (PMID 30034996, 2018). "Importantly, the level of TUBB3 expression was heterogeneous in leiomyosarcoma patients and it is reasonable to infer that sensitivity to eribulin might be negatively associated with TUBB3 expression level." (PMID 30034996, 2018).
liver cancer (1 paper, 2019). An epithelial or non-epithelial malignant neoplasm that arises from the liver. "Up-regulation of TUBA6, TUBA8, and TUBB3 has been reported in human liver cancer." (PMID 31191608, 2019).
lung fibrosis (1 paper, 2025). "Compared to healthy individuals, higher proportions of TUBB3+ pericytes were observed in patients with SSc-associated pulmonary fibrosis and IPF." (PMID 41472685, 2025). "Tuj1 expression is predominantly induced in pericytes during the fibrotic phase, and Tuj1 gene (Tubb3) knockout in mice exacerbates lung fibrosis, accompanied by an increase in the neighboring pro-fibrotic fibroblasts and macrophages, suggesting an anti-fibrotic role for Tuj1-expressing pericytes." (PMID 41472685, 2025). "Intriguingly, genetic ablation of Tuj1 gene (Tubb3) significantly exacerbated lung fibrosis." (PMID 41472685, 2025). "To address whether Tuj1 expression in lung pericytes influences the fibrotic process, we analyzed bleomycin-induced pulmonary fibrosis in the mutant mice lacking Tuj1 (Tubb3−/− mice)." (PMID 41472685, 2025).
Lymphatic Metastasis (1 paper, 2014). Transfer of a neoplasm from its primary site to lymph nodes or to distant parts of the body by way of the lymphatic system. "With regard to TUBB3 expression levels, a negative association was observed with lymphatic metastasis (r=−0.42, P=0.0231)." (PMID 24926347, 2014).
MELAS (1 paper, 2025). "Our previous data demonstrated that iPSCs derived from MELAS patients with a higher percentage of m.13513G>A mtDNA (≥84%) showed poor differentiation into αSMA-positive cells and TUBB3-positive neuronal cells with extended neurites." (PMID 40242044, 2025).
metastasis (1 paper, 2018). The spread or migration of cancer cells from one part of the body (where they first appeared) to another. "In the RNA sequencing data genes linked to arteries (Elastin, Lamb1, Acta2), pericytes (Cspg4/Ng2, Pdgfrb, Sca1 (Ly6a)) and neurons/neurites (Gap43, Tubb3) were up-regulated in the stroma of osteolytic bone metastasis." (PMID 29988965, 2018).
metastatic cancer (1 paper, 2023). A carcinoma which has spread from the original site of growth to another anatomic site. "However, the ASE “TUBB3_ES_38175” generated a TUBB3 mRNA isoform that could be removed by NMD, and was down-regulated in metastatic cancer." (PMID 37810965, 2023).
nervous system injuries (1 paper, 2023). "Therefore, Tubb3 has a specific function for the development of the nervous system and the maintenance of the axons, and in the case of central nervous system injuries, Tubb3 could have a preponderant function in the maintenance of the cytoarchitecture and/or in a possible functional recovery." (PMID 37288064, 2023).
neurofibroma (1 paper, 2012). An intraneural or extraneural neoplasm arising from nerve tissues and neural sheaths. "Previous studies have reported the mRNA expression of NEFM and tubulin in SCs and TUBB3 expression in neurofibroma SCs." (PMID 22443529, 2012).
neuropathies (1 paper, 2013). "Therefore, MT motors are essential for neuronal longevity, as is also indicated by the numerous mutations in kinesin and dynein/dynactin genes which link to neuropathies and neurodegeneration, as well as by the fact that the H12 loop mutations of TUBB3 link to neuropathies." (PMID 24010872, 2013).
prostate tumor (1 paper, 2022). "The expression of TUBB3 is reported to be not only associated with the progression of CRPC in a study enrolling 138 human prostate tumor specimens but is also able to predict the treatment response to taxene-based chemotherapy for CRPC." (PMID 35326723, 2022).
pulpitis (1 paper, 2023). Inflammation of the dental pulp. "Here, we also observed a trend (although not statistically significant) in the recovery of the mRNA level of the pan-neural marker TUBB3 when treated with CNC PCs in pulpitis model mice, which needs to be further verified by long-term experimental observation." (PMID 38137420, 2023).
Renal neoplasm (1 paper, 2021). The presence of a neoplasm of the kidney. "By setting a staining score cutoff > 2 (equivalent to > 10% of cells staining positive) for TUBB3, this biomarker has a sensitivity of 53.8% and a specificity of 100% in distinguishing pRCC from other renal neoplasms." (PMID 34482820, 2021).
tongue squamous cell carcinoma (1 paper, 2024). A squamous cell carcinoma that arises from the tongue. "In tongue squamous cell carcinoma (TSCC), exosomal miR-200c may be an effective strategy for suppressing chemoresistance to docetaxel, as it inhibits TUBB3 and PPP2R1B." (PMID 38429738, 2024).
urogenital cancers (1 paper, 2023). "Furthermore, we identified and validated alternative splicing of TUBB3 and RNA binding proteins such as PCBP2 as critical regulators in the progression of urogenital cancers." (PMID 37810965, 2023). "Furthermore, we identified alternative splicing of GIT2 and TUBB3 and RNA binding proteins such as PCBP2 as critical regulators in the progression of urogenital cancers." (PMID 37810965, 2023).
Vestibular schwannoma (1 paper, 2015). A vestibular schwannoma (also known as acoustic neuroma, acoustic neurinoma, or acoustic neurilemoma) is a benign, usually slow-growing tumor that develops from the VIIIth cranial nerve supplying the inner ear. "Finally, TUBB3 expression in HDF-a was 14-fold higher (p<0.001) than in human vestibular schwannoma (bottom)." (PMID 26678612, 2015).
tumor (90 papers, 2007 to 2025). "The study showed that under the induction of tumor secretions, a specific subset of tumor-associated macrophages that express Tubb3 and lose macrophage markers is generated in the TME." (PMID 38081962, 2024). "Prognostic genes associated with C3 were identified, among which TUBB3 is implicated in potential resistance to tumor recurrence." (PMID 38562930, 2024). "TUBB3 is frequently overexpressed in human tumors and is associated with resistance to microtubule-targeting agents, tumor aggressiveness, and poor patient outcomes." (PMID 38001941, 2023). "Of note, one particular isotype, βIII-tubulin, encoded by the TUBB3 gene, has demonstrated aberrant expression in the clinical setting, and has been identified as a marker of drug resistance and tumour aggressiveness in a sub-set of epithelial cancers." (PMID 35573698, 2022). "Neurogenesis is crucial for cancer pain development and tumor progression, where tumoral Tubb3 expression and MNT levels are highly associated with the mortality in NSCLC." (PMID 36206343, 2022). "TubB3 overexpression has been linked to aggressive tumor features, genetic instability, and poor prognosis in urinary bladder cancer and clear cell renal cell carcinoma." (PMID 35008169, 2021). "TMB‐H and TUBB3 positive were associated in 2 of 40 tumor types; hence, combinations of taxanes and immunotherapy are not beneficial." (PMID 31479512, 2020). "In univariate analysis, high tumor budding and TUBB3 expression were associated with inferior progression-free survival in cPTC." (PMID 33256003, 2020). "In cPTCs, higher TUBB3 expression was correlated with stromal TUBB3 expression, higher tumor budding, and positivity for BRAF mutation-specific antibody (all p < 0.05)." (PMID 33256003, 2020). "In univariate analysis, high TUBB3 H-score and tumor budding were associated with inferior progression-free survival (PFS; both p < 0.05)." (PMID 33256003, 2020). "Immunohistochemical analysis revealed that β-tubulin-III (TUBB3) expression was higher in GAC than in benign gastric mucosa lesions, which had been associated with resistance to docetaxel-based chemotherapy." (PMID 32751679, 2020). "In this sample set, the expression of TUBB3 was significantly associated with a high Gleason score (p = 0.048) and high tumor stage (p < 0.001)." (PMID 31412591, 2019). "Enhanced TUBB3 expression (Score 3) is significantly associated with an advanced depth of tumor infiltration (p<0.003) and the existence of lymph node metastases (p=0.023)." (PMID 29383151, 2017). "Preliminarily, we observed the regression of tumor growth using a small-size sample group in TUBB3-deficient subcutaneous tumors." (PMID 27284014, 2016). "In our study, we did not fiund the association between expression levels of RRM1 and TUBB3 and tumor response to chemotherapy and clinical outcome of advanced NSCLC." (PMID 25674147, 2014). "Single gene analysis indicated that ERCC1 and TYMS expression levels were associated with the depth of tumor invasion, while TUBB3 expression was associated with the lymphatic metastasis of ESCC." (PMID 24926347, 2014). "Indeed, efforts have been made to identify such biomarkers; for example, overexpression of class III β-tubulin (encoded by TUBB3) or anti-apoptotic proteins in tumours has been linked to poor responses (as discussed later)." (PMID 40806254, 2025).
tumor (continued). "We demonstrated that pharmaceutical inhibition of Smad3 with the specific inhibitor SIS3 effectively blocked MNT as well as the associated tumor innervation (Tubb3+ and NeuN+ cells) and cancer-associated spontaneous nocifensive behaviors of the LLC-bearing mice." (PMID 36206343, 2022). "Snail and Slug both present as interesting regulators of TUBB3, as they are both expressed in a large range of cancers, and also because of their roles in the epithelial–mesenchymal transition in tumour cells, the process linked with metastasis." (PMID 35573698, 2022). "In addition, TUBB3 is mostly associated with malignant tumour features, such as tumour growth, migration and invasion and poor outcomes." (PMID 36139331, 2022). "In a panel of normal and tumor cells that were primarily derived from the lung and prostate, we found that P-gp-associated drug-resistant (PacR and GefR) cancer cells express higher TUBB3 and FOXO3a levels compared to drug-sensitive normal cells." (PMID 27284014, 2016). "However, the role of TUBB3, which is the most studied isotype in solid tumours and is also a marker of biological aggressiveness associated with the modulation of tumour metastatic abilities in the growth and development of platyhelminths, is unknown." (PMID 36139331, 2022). "Enhanced OSGIN-1-mediated binding between DYRK1A and TUBB3 induces phosphorylation of TUBB3 serine 172, which effectively reduces tubulin polymerization, a mechanism of tumor migration and invasiveness." (PMID 40149945, 2025). "Experimental research on anti-microtubule chemotherapy drugs has revealed that tumor cells with high TUBB3 expression exhibit stronger resistance to drugs like paclitaxel compared to those with lower expression." (PMID 38562930, 2024). "We compared the expression levels of the CD99, CDKN1A, NES, SOX2, and TUBB3 genes in ES tumor samples and controls consisting of normal muscle tissue." (PMID 38785514, 2024). "Elevated levels of TUBB3 have been correlated with a more aggressive tumor phenotype and resistance to specific chemotherapy drugs." (PMID 37444584, 2023). "In tumor tissues, TUBB3 was significantly higher than that in adjacent tissues, while patients with high levels of TUBB3 were at higher risk." (PMID 35945754, 2022). "Deregulation of TUBB3 in tumorigenicity and tumor progression are often coupled with the prevalence of SFK dysfunction in a similar spectrum of cancers." (PMID 35631517, 2022). "TUBB4 downregulation and upregulation of TUBB3 results in epithelial-mesenchymal transition of tumor cells and tumor metastasis in colon cancer." (PMID 36506940, 2022). "It was found that the presence of TUBB3 and RRM1 deletion in tumor biopsy material is associated with more effective treatment." (PMID 35204496, 2022). "In tumours, the hypoxia-inducing factor HIF1α has been implicated in the transcriptional regulation of βIII-tubulin via the 3′UTR of the TUBB3 gene and is thought to protect tumours against hypoxic injury." (PMID 35573698, 2022). "On the basis of experimental research, this study detected molecular markers (ERCC1, RRM1, and TUBB3 mRNAs) in tumour tissue specimens from patients who needed adjuvant chemotherapy after surgery." (PMID 34603450, 2021). "Whilst these results were promising, growing clinical evidence indicates high expression of TUBB3 as a clinical biomarker of taxane resistance in various tumour types, but has been shown to predict sensitivity to epothilone B compounds." (PMID 34154646, 2021). "The close relationship between the TUBB3 mRNA expression level and the resistance to antimicrotubule agents in chemotherapy, especially paclitaxel, has been confirmed in many tumour cell lines and clinical studies." (PMID 34603450, 2021). "Tumour patients with low expression of TUBB3 have a better response to paclitaxel and have longer median survival times, while the efficacy of antimicrotubule agents is poor for patients with high TUBB3 expression." (PMID 34603450, 2021).